GDF15 (growth differentiation factor 15)
Diseases named in the same sentence as GDF15 in open-access papers (continued):
Sharing a sentence is not in itself a finding about the gene and the disease.
anemia (continued). "Furthermore, the GDF15 was implicated in the pathogenesis of anemia by inhibiting the expression of hepcidin." (PMID 36140453, 2022). "New biomarkers of ferric management, namely, soluble transferrin receptor (sTfR), growth differentiation factor 15 (GDF15) and hepcidin 25, may correlate with characteristics in the etiology and management of MM-associated anaemia." (PMID 31683939, 2019). "Therefore, an increased GDF-15 level as well as iron deficiency might be useful markers for the screening of anemia, which is common in older adults." (PMID 38883134, 2024). "We postulate that GDF-15 may parallel the underlying mechanisms of myeloma pathology occurring in the abnormal ME, and as such, it shares a relationship with tumor burden and disease complications, most prominently related to anemia and kidney injury." (PMID 33144847, 2020). "At the cardiac level, GDF15 has been proposed as a potential indicator of worse prognoses in patients with HF and concurrent anemia." (PMID 41008541, 2025). "Higher GDF15 values were correlated to anaemia among patients with CKD, with values greater than 723 pg/mL suggestive of anaemia." (PMID 40019842, 2025). "GDF15 is increased in serum from patients with ID and its circulating levels have been studied in the context of HF and concurrent anemia." (PMID 41008541, 2025). "Results indicate that both drugs had insignificant difference in their effect on CKD pediatric anemia after 3 months of treatment except the effect on IL-6, GDF-15, TSAT, and GFR." (PMID 39910177, 2025). "It highlights the role of key regulatory factors such as hepcidin, erythroferrone (ERFE), and growth differentiation factor 15 (GDF-15) in anaemia and erythropoiesis." (PMID 39940645, 2025). "Due to the cross-sectional nature of the study design, further studies are needed to validate the utility of GDF-15 and hepcidin as biomarkers of anemia in older adults." (PMID 38883134, 2024). "The mechanisms involved in the effects of GDF-15 on anemia have been investigated in several studies." (PMID 38883134, 2024). "The study aims to determine the discriminatory thresholds, specificity, and sensitivity of the novel biomarkers FGF21, GDF15, and NOS in diagnosing mitochondrial dysfunction associated with pediatric anemia." (PMID 39124668, 2024). "The increasing GDF-15 level was determined by a decrease in the hepcidin level as well as by anemia and renal dysfunction, and the decreasing hepcidin level was determined by a decrease in stored iron and a decrease in serum albumin level." (PMID 38883134, 2024). "Hepcidin is a regulator of iron metabolism, and growth differentiation factor-15 (GDF-15) is a biomarker for anemia." (PMID 38883134, 2024). "In that study, multivariate logistic regression analysis found that Hb (β=-0.34), GDF-15 (β=-0.3), and hepcidin (β=-0.26) were predictors of anemia in patients with CKD." (PMID 38883134, 2024). "Anemia in community-dwelling older adults was determined not only by increasing serum iron levels but also by decreasing GDF-15 levels." (PMID 38883134, 2024). "Serum hepcidin and GDF-15 predicted anemia among patients with CKD, with a predictive value of 72% and 76.47%, respectively." (PMID 37649102, 2023). "More extensive studies are necessary to determine a reliable cut-off value of serum hepcidin and GDF-15 in anemia diagnosis." (PMID 37649102, 2023). "The predictive value of hepcidin and GDF-15 for diagnosing anemia among CKD participants was 72.0%, 76.47% respectively." (PMID 37649102, 2023). "We also found that GDF-15 predicted anemia at a cut-off value < 724 pg/ml with a predictive value of 70.0%, sensitivity of 82.98%, and specificity of 87.11%." (PMID 37649102, 2023). "Hepcidin and GDF-15 is a potential biomarker for predicting anaemia connected with inflammation among CKD Egyptian patients." (PMID 37649102, 2023).
anemia (continued). "Our findings indicate that GDF-15 is a promising prognostic marker in patients with chronic HF and anemia, with correlation to indices of iron metabolism." (PMID 34611778, 2022). "In patients with HF and anemia, both higher baseline serum GDF-15 levels and an increase in GDF-15 during follow-up, were associated with worse clinical outcomes." (PMID 34611778, 2022). "Serum GDF-15 concentrations were significantly higher in the studied patients with anemia and inversely correlated with blood hemoglobin and serum iron." (PMID 33144847, 2020). "Emerging evidence shows that in response to anaemia, erythroblasts secrete GDF-15, which in turn suppresses hepcidin expression and decreases iron stores." (PMID 32993549, 2020). "Serum GDF-15 levels are elevated in disorders of ineffective erythropoiesis such as thalassemia, and GDF-15 is a possible mediator of anemia through hepcidin in adult renal transplant recipients." (PMID 32089755, 2020). "In that study, GDF-15 was related to anemia and hepcidin, indicating its involvement in the pathogenesis of anemia." (PMID 32089755, 2020). "GDF-15 was significantly higher in patients with anemia according to WHO definition (Hb less than 12 g/dl in women and 13 g/dl in men) in comparison with their non-anemic counterparts." (PMID 27043030, 2016). "We found that GDF-15 levels were significantly higher in elderly patients with CKD as well as in patients with anemia." (PMID 27043030, 2016). "PMF patients with advanced disease with more severe anemia tended to show higher serum GDF15 levels." (PMID 26276681, 2015). "GDF-15 levels at the ICU were significantly higher in patients who presented anemia during the postoperative period (p = 0.010); moreover, higher GDF-15 concentrations correlated with lower ICU plasma hemoglobin (r = −0.456, p = 0.007)." (PMID 25171167, 2014). "Although only non-anemic ID patients were included in the analysis, the inverse relationship between GDF15 and hemoglobin levels supports that GDF15 may reflect to some extent the anemia status." (PMID 41008541, 2025). "Also, the increasing GDF-15 level was determined by a decreasing hepcidin level as well as the presence of anemia and renal dysfunction, and the decreasing hepcidin level was determined by decreasing stored iron and decreasing albumin levels." (PMID 38883134, 2024). "A significant association between GDF-15 and hepcidin has not been reported for patients with inflammatory and iron-deficiency anemia or with CKD." (PMID 38883134, 2024). "Thus, in community-dwelling older adults, anemia was determined not only with low serum iron but also with high serum GDF-15 levels." (PMID 38883134, 2024). "A recent study of patients with CKD that examined the association between anemia, GDF-15, and hepcidin found significant correlations between hepcidin levels and iron and CRP and significant correlations between serum GDF-15 and Hb levels, ferritin, iron, and CRP." (PMID 38883134, 2024). "Thus, serum GDF-15 was determined not only by anemia and impaired renal function but also by decreased serum hepcidin levels." (PMID 38883134, 2024). "In patients aged over 60, GDF15 emerged as a standalone predictor of anemia." (PMID 39124668, 2024). "However, studies demonstrating a relationship between GDF-15 expression and serum iron parameters will assist to shed more light on the investigation, treatment and monitoring of anemia in CKD patients." (PMID 37649102, 2023). "The role of GDF-15 in the evolution of anemia is still controversial." (PMID 37649102, 2023). "Anemia involved in renal dysfunction and chronic inflammation is reportedly associated with high GDF-15 levels, while iron deficiency anemia is not." (PMID 37396418, 2023). "Besides, in response to anemia, erythroblasts secretes GDF-15, which in turn suppresses hepcidin expression and decrease iron stores." (PMID 37649102, 2023). "GDF-15 and hepcidin is involved in inflammatory response that play an important role in anemia." (PMID 37649102, 2023).
anemia (continued). "We evaluated the diagnostic validity of growth differentiation factor-15 (GDF-15) and hepcidin as it is not clear if they are useful as a biomarkers of anaemia among non-dialysis CKD egyptian patients." (PMID 37649102, 2023). "Furthermore, high levels of GDF-15 are reported in patients with HF and anemia, correlated with iron status." (PMID 34611778, 2022). "GDF15 can be significantly upregulated by anemia and hypoxia." (PMID 34445593, 2021). "Moreover, we studied the correlations between GDF-15 and the acclaimed and emerging biomarkers of important clinical manifestations of MM, i.e., anemia and renal impairment." (PMID 33144847, 2020). "Induction of hepcidin by GDF-15 may potentially limit the availability of iron for hematopoiesis and provide an alternative explanation for the relationship with anemia." (PMID 33144847, 2020). "The ability GDF15 to contribute to anaemia’s development may follow from its regulation of hepcidin expression." (PMID 31683939, 2019). "Impaired glucose tolerance is associated with increased GDF-15 levels even in the absence of anemia, but the levels of hepcidin are not significantly altered in prediabetic state." (PMID 27642607, 2016). "However, in our study GDF-15 levels are significantly increased in patients with anemia that is in line with other research." (PMID 27043030, 2016). "In conclusion, impaired glucose tolerance is associated with increased GDF-15 levels even in the absence of anemia, but the levels of hepcidin are not significantly altered in prediabetic state." (PMID 27642607, 2016). "Similar to our present study GDF-15 was significantly higher in patients with anemia." (PMID 27043030, 2016). "The combination of ineffective erythropoiesis (leading to increased GDF15) and chronic anaemia/hypoxia (altering the expression of HIF) results in hepcidin suppression, increased iron absorption and increased release of recycled iron from the reticuloendothelial (RE) system." (PMID 21415986, 2009). "Conversely, isolated iron deficiency anemia did not significantly alter GDF15 levels." (PMID 39124668, 2024). "The change in serum FGF21 and GDF-15 in anemia or iron deficiency anemia is not reported." (PMID 39124668, 2024). "Therefore, anemia, GDF-15, and hepcidin have significance in aging physiology." (PMID 38883134, 2024). "There are possible mechanisms that may explain the findings of increased GDF-15 in anemia." (PMID 37649102, 2023). "However, hypoxia and anemia activate the expression and synthesis of GDF15." (PMID 36140453, 2022). "GDF-15 did not identify subgroups of patients who might benefit from correction of anemia but was associated with several indices of anemia and iron status in the HF patients." (PMID 34611778, 2022). "Finally, GDF15, by affecting iron status, might be involved in the pathogenesis of anemia in patients with cardiovascular diseases." (PMID 34445593, 2021). "In elderly individuals with anemia of unknown etiology, the moderate elevation of GDF-15 was observed, the latter being strongly correlated with kidney function (creatinine), which was surmised to indicate a mutual relationship between anemia and renal insufficiency." (PMID 33144847, 2020). "Furthermore, GDF-15 predicted AID anaemia, while hepcidin predicted FID anaemia (83.6% vs 66.7%)." (PMID 32993549, 2020). "Preliminary studies have indicated the clinical potential of measuring GDF15 to predict disease progression and outcomes, which may also indirectly influence an assessment of anaemia, as reducing bone marrow infiltration by malignant cells should improve haematopoiesis." (PMID 31683939, 2019). "Furthermore, unlike the senior demographic, no apparent association between GDF15 and anemia which was observed in the pediatric group in our research, which may be due to the limited small number of patients." (PMID 39124668, 2024).
anemia (continued). "This study aims to explore the correlation between pediatric anemia and mitochondrial markers, specifically fibroblast growth factor 21 (FGF21), growth/differentiation factor 15 (GDF-15), and nitric oxide synthase (eNOS)." (PMID 39124668, 2024). "The predictive value of diagnosing anaemia among CKD patients using hepcidin and GDF-15 was 72.0%, 70.0%." (PMID 37649102, 2023). "Serum GDF-15 levels were significantly elevated in patients with low body weight, severe CKD, moderate to severe anemia, HF, anticipated use of long-term oral anticoagulation, and PVD." (PMID 37396418, 2023). "Two proteins produced by erythroid precursors, growth differentiation factor 15 (GDF15) and twisted gastrulation protein (TWSG1), have been proposed to mediate hepcidin suppression in anemias with ineffective erythropoiesis." (PMID 20066043, 2010). "In patients with anemia without inflammation, GDF-15 was produced and released in response to anemia or hypoxia." (PMID 38883134, 2024). "Log GDF-15 decreased with every unit increase of MCHC (β = 0.0196, P-value = 0.005) this explained by cytokine blocks hepcidin expression and increases iron absorption, thus leading to iron loading in these anemias." (PMID 37649102, 2023). "Average serum hepcidin-25 level was more than twice higher in patients with anemia than in those without anemia; similar differences were observed between the groups in serum concentrations of IL-6 and GDF-15." (PMID 35334593, 2022). "In other study on 134 stable heart transplant recipients and 157 patients with chronic heart failure, GDF-15 was significantly higher in patients with anemia compared with non-anemic counterparts in both groups." (PMID 27043030, 2016). "GDF-15 was significantly higher in patients with anemia in comparison with their non-anemic counterparts." (PMID 27043030, 2016). "Both treatments are effective in treating CKD-induced anemia in pediatrics; however, oral lactoferrin demonstrated superior efficacy as there was a significant change within that group in levels of Hb, RBCs, MCH, iron, RDW-SD, MCHC, IL-6, and GDF-15 before and after treatment." (PMID 39910177, 2025). "A significant gap exists in the current literature regarding the association between mitochondrial dysfunction and anemia in a dominant pediatric population with iron deficiency anemia, as evidenced by the absence of studies utilizing the markers of FGF21, GDF-15, and NOS." (PMID 39124668, 2024). "In contrast, moderately elevated GDF-15 levels were not significantly correlated with hepcidin expression in older patients with anemia of unknown origin." (PMID 38883134, 2024). "It has been suggested that anemia may have an effect on the hepcidin and GDF-15 levels, but no data is available regarding the hepcidin and GDF-15 levels and their possible relationships in nonanemic subjects with prediabetes." (PMID 27642607, 2016). "However, moderately increased GDF-15 in anemia of unknown origin was not significantly correlated with hepcidin expression." (PMID 41517557, 2025). "However, anemia did not improve lifespan, ataxia, or Gdf15 levels." (PMID 37260376, 2023). "Although the GDF-15 assay was not calibrated against a universal standard, it is possible that the additional burden of anemia could have contributed to the elevated levels GDF-15 levels in the present study as compared to HF patients without anemia as also has been suggested by others." (PMID 34611778, 2022). "According to earlier research very high levels of GDF-15 suppressed the expression of hepcidin, whereas moderately elevated GDF-15 concentration were positively correlated with hepcidin in kidney allograft recipients and in elderly individuals with anemia of unknown origin." (PMID 27043030, 2016).
glioblastoma (41 papers, 2010 to 2025). The most malignant astrocytic tumor (WHO grade IV). "GDF15 silencing was shown to be associated with improved survival and increased infiltration of T-cells and macrophages in a glioblastoma syngeneic mouse model." (PMID 39516530, 2024). "Since hypoxia is a hallmark of glioblastoma, we defined the impact of hypoxic conditions on GDF-15 expression levels in vitro." (PMID 26741507, 2016). "Using a TCGA database interrogation, we demonstrate that high GDF-15 expression levels are associated with poor survival of glioblastoma patients." (PMID 26741507, 2016). "Analysis of the gene expression dataset deposited in the TCGA database demonstrated that high GDF-15 levels are associated with reduced overall survival of glioblastoma patients." (PMID 26741507, 2016). "More importantly, glioblastoma patients have been shown to have increased GDF15 levels in their blood while higher GDF15 mRNA expression inside the tumor has been associated with poor survival, suggesting that GDF15 likely possesses tumor-promoting properties." (PMID 31412547, 2019). "It has been reported that GDF15 is highly expressed in high-grade gliomas such as glioblastoma multiforme (GBM) and correlated with poor prognosis." (PMID 41009755, 2025). "Conversely, elevated GDF15 levels in glioblastoma patients are correlated with a poor prognosis, immune suppression, and increased invasion." (PMID 40430278, 2025). "For instance, in glioblastoma studies, GDF15 overexpression was shown to impede tumor growth and reduce tumor volume in immunocompromised mouse models." (PMID 40144214, 2025). "GDF-15 methylation has been suggested to be involved in several cancers, including bladder cancer, urothelial cancer, and glioblastoma." (PMID 39728572, 2024). "One study aiming to explore the immunologic role of GDF15 in glioblastoma models revealed that GDF15 promotes the expression of PD-L1 through activation of the SMAD2/3 signaling pathway." (PMID 36353620, 2022). "Downregulation of GDF15 was found to improve T-cell infiltration into transplantable glioblastoma, prolonging survival and enhancing the immune response." (PMID 36353620, 2022). "Subsequently, GDF15 activated the transcriptional promoter VEGFA in the human glioblastoma cell line U373 through p-MAPK1/SP1 signaling." (PMID 35280749, 2022). "GDF-15 inhibits dendritic cell maturation in the TME leading to impaired T cell activation, whereas, downregulation of GDF-15 using short hairpin RNA (shRNA) in a glioblastoma model resulted in increased T cell infiltration in the TME and increased survival." (PMID 35743911, 2022). "This study examined the role of radiation-induced growth/differentiation factor-15 (GDF15) in regulating tumor angiogenesis by promoting intercellular cross-talk between brain endothelial cells (ECs) and glioblastoma cells." (PMID 35280749, 2022). "Growth differentiation factor (GDF15) is highly expressed in glioblastoma as a secreted cytokine participate in regulating tumor cell proliferation and immunosuppression." (PMID 34532286, 2021). "Studies to date have shown approximately 50% increased GDF15 levels in CSF of patients with neurodegenerative disorders or glioblastomas." (PMID 34043633, 2021). "In these studies GDF15 was shown to be increased in CSF of patients with neurodegenerative disorders such as multiple sclerosis and Parkinson’s disease or in glioblastoma patients." (PMID 34043633, 2021). "A further study in transplantable glioblastoma revealed that shRNA-mediated downregulation of GDF-15 increased T cell infiltration into tumors, improved immune responses and prolonged survival." (PMID 32508832, 2020). "In the context of glioblastoma, we have characterized GDF-15 as a molecule that contributes to the local immunosuppressive environment surrounding gliomas pointing to a mostly paracrine mode of action." (PMID 26741507, 2016).